INS (insulin)
Diseases named in the same sentence as INS in open-access papers (continued):
Sharing a sentence is not in itself a finding about the gene and the disease.
tumor (continued). "Moreover, it has been previously observed that TNFα is associated with NOx synthesis activity through a variety of pathways, most commonly through the activation of Akt at Ser 473, a signaling pathway involved in several metabolic activities, including tumor growth and insulin resistance." (PMID 36832339, 2023). "The hypothesis underpinning our study was that higher FABP-4 may be positively associated with CRC risk, which could be biologically explained by facilitating tumor growth via increased fatty acid supply, or FABP-4-related enhancement of inflammation and insulin resistance." (PMID 37833736, 2023). "However, metformin had a multitude of additional effects including abrogating weight gain, adiposity, hepatic steatosis, and oncogenic signaling in the pancreas, confounding the interpretation that normalizing insulin levels were the driving force behind its anti-tumor effects." (PMID 37648285, 2023). "Indeed, insulin is a growth factor, and the administration of exogenous insulin could, at least theoretically, stimulate tumour growth." (PMID 38146457, 2023). "Here, we show that tumours induced by the overexpression of RasV12 and an RNAi against the polarity protein Scribble (scribRNAi) using the QF/QUAS system, caused a downregulation of insulin signalling (pAkt), and an upregulation of TGF‐β signalling (pMad) in the fat body." (PMID 38014610, 2023). "Potentially beneficial biological mechanisms of exercise on cancer are the modulation of insulin/glucose metabolism and thus reducing obesity, inflammation, and oxidative stress, which reduces tumor growth, the activation of tumor suppressor genes, and an increase in apoptosis in tumor tissue." (PMID 37553660, 2023). "Consequently, the relationship between PIK3C2A, ubiquitin, insulin, and the mTOR signaling pathway may be an important modulator of tumor immunity." (PMID 37063922, 2023). "Moreover, both androgens and estrogens are hypothesized to prevent tumor growth in part by preventing insulin and insulin-like growth factor (IGF) from binding to their receptors and there is evidence of an association between IGF-1 and the risk of CRC." (PMID 37341814, 2023). "In patients treated with metformin there was an increase in the expression of tumour pAMPK, reduction in pAkt and suppression of insulin responses, as well as a significant decrease in Ki67 and cleaved caspase-3, suggesting that metformin may exert a cytostatic anti-tumour effect." (PMID 37173907, 2023). "Finally, in tumour bearing animals fed a sterol‐free diet, that underwent a prolonged 3rd instar stage due to reduced ecdysone levels, we activated insulin signalling in the fat body via Akt overexpression (QRasV12, scribRNAi)." (PMID 38014610, 2023). "Metformin has the capacity to reduce tumour proliferation in a multitude of mechanisms that include reducing circulating insulin and glucose levels as well as regulating the expression of various cell signalling pathways involved in the regulation of insulin and glucose metabolism." (PMID 35610365, 2022). "If the “direct action” hypothesis were correct, one would predict a similar effect of SGLT2 inhibition to slow tumor growth regardless of whether the driver mutation is related to insulin and/or glucose metabolism." (PMID 35595952, 2022). "Interestingly, the2D-monolayer culture showed higher absolute insulin secretion after glucosechallenge, possibly due to the tumor origin of the 2D adhesive cell line, ahigher surface to volume ratio, and enhanced stimulus conduction of confluentmonolayer cells." (PMID 35462988, 2022). "Moreover, serum glucose (R2 = 0.22, p < 0.01) and leptin (R2 = 0.22, p < 0.01) levels was associated with tumor volume, while no such association was observed for insulin." (PMID 35361802, 2022). "In addition, tumor size may alter insulin secretion by inducing atrophy or destruction of the pancreas." (PMID 36422243, 2022).
tumor (continued). "The Yki-dependent activation of progenitor cells is controlled by insulin-driven Akt signaling, indicating that Akt has a role in restricting proliferation and migration of progenitor cells, although it is originally identified as an oncogene and promotes tumor progression." (PMID 35595807, 2022). "Also, increased levels of bioavailable oestrogens in early adulthood (associated with insulin levels and decreased sex hormone binding globulin) could induce earlier differentiation of mammary cells and expression of the BRCA1 tumour suppressor gene." (PMID 34072619, 2021). "Also, we investigate whether IGFBP7 messenger ribonucleic acid (mRNA) expression is associated with the patient and tumor characteristics and other proteins in the IGF/insulin-signaling pathway." (PMID 34606580, 2021). "Additionally, insulin is involved in tumor development by directly or indirectly affecting endogenous estrogen metabolism and promoting the expression of endometrial estrogen receptor (ER), which in turn enhances the function of estrogen in the tumorigenesis of EC." (PMID 34917501, 2021). "Notably, treatment with either ICI or OSI‐906 prevented tumor growth induced by E2 and insulin." (PMID 34841688, 2021). "Therefore, only tumours with heavy staining and clonal expansion of such cells may contain sufficient amounts of insulin." (PMID 34170845, 2021). "In addition to chemotherapy, the tumor itself can negatively affect cardiac insulin signaling." (PMID 33547494, 2021). "Additionally, tumor cells' characteristics such as receptors (insulin/IGF1) and pathway proteins (PI3K/mTOR, LKB1, and TSC2) expression might potentially mediate these indirect, host-mediated effects and any direct effects that are extremely important." (PMID 33531904, 2021). "Insulin and its analogues may function as growth factors and therefore have a theoretical potential to promote tumor proliferation through various mechanisms involving activation of the insulin receptor, IGF-1 receptor (IGF-1R) and extracellular-signaling-regulated kinase (ERK) pathways." (PMID 34535145, 2021). "Therefore, insulin plays critical roles in tumor growth via the PI3K signaling pathway." (PMID 32842547, 2020). "However, these agents exhibited far lower efficacy than expected, possibly due to activation of alternative pathways that compensate for the PIK3-AKT pathway and allow tumor growth, or due to adaptive mechanisms including the insulin feedback pathway that limits the efficacy of agents." (PMID 32842547, 2020). "Insulin increases cell proliferation and reduces apoptosis, which may lead to tumor development." (PMID 33238496, 2020). "In addition, tumor mass may influence normal insulin secretion by inducing destruction or atrophy of pancreatic parenchyma." (PMID 33424776, 2020). "Furthermore, some in vitro studies have shown that insulin might also stimulate the mitogenesis of cultured normal colorectal epithelial cells and tumor angiogenesis." (PMID 32340309, 2020). "Additionally, multiple known endocrine hormones, such as insulin, prostaglandins, glucocorticoids, prolactin, and progesterone, have been observed to play a role in cancers by modulating malignant phenotypes or anti-tumor immune responses." (PMID 33117814, 2020). "Accelerated tumour development or its higher aggressiveness may stem from dysregulation of multiple pathways, e.g., the upregulation of oestrogen and insulin levels and other growth factors secreted from adipose tissue, abnormal cholesterol metabolism, and immune system disturbances." (PMID 33008076, 2020). "In our study, we did not observe any significant association with neoplasm in insulin users." (PMID 33424764, 2020). "We also investigated the levels of tumor suppressors and protooncogenic proteins HBlEpC after treatment with pioglitazone or metformin to determine whether carcinogenesis occurs under high-glucose and insulin conditions." (PMID 30729133, 2019).
tumor (continued). "However, it remains to be further investigated whether the anti-tumor response of canagliflozin is due to the direct impact on tumor cell SGLT2 or systematic effect on the blockade of feed-back insulin induction." (PMID 31569510, 2019). "Thus, this study reports for the first time the mechanism by which insulin may increase the invasive potential of tumor cells." (PMID 31379747, 2019). "Metastatic tumor masses along with the production of peptide hormones, such as gastrin, somatostatin, insulin, glucagon, or vaso inhibitory peptide (VIP) by tumor cells, may lead to severe symptoms and complications, such as diarrhoea, gastric ulcers, flush, diabetes, or hypoglycaemia." (PMID 31527438, 2019). "However, most of these models showed the presence of some commonalities among the long-lived mice, such as reduced circulating IGF-1 and insulin levels and increased insulin sensitivity, which likely contribute to reduce tumor incidence, to improve stress resistance and to extend the lifespan." (PMID 30774624, 2019). "It has been hypothesized that metformin could act with both direct and indirect mechanisms, primarily decreasing glucose, IGF-1 and insulin signaling, thereby creating an unfavorable environment for tumor growth that is similar to that created by caloric restriction." (PMID 30635619, 2019). "If just a minor clone within a tumor has acquired independence of these external controls; then even if blockade of insulin/IGFs were effective for the major clones and initially shrank the tumor, it could also add a selective advantage to these minor clones which could then regenerate the tumor." (PMID 30809194, 2019). "This endocrine function of skeletal muscle may underlie numerous health benefits such as maintaining adequate body weight, reducing low-grade inflammation typical of chronic diseases, improving insulin sensitivity, protecting from tumor growth, and improving cognitive function." (PMID 31849710, 2019). "It was later demonstrated that activation of salt-inducible kinase in tumours from animals fed a high sugar diet functions to inhibit Hippo signalling, which facilitates the increase in Wg signalling that mediates the evasion of insulin resistance by these tumours." (PMID 29725601, 2018). "Therefore, the ability of biguanides to lower both glucose and insulin levels may indirectly contribute to its anti-tumor effects." (PMID 29423103, 2018). "Thus, accumulation of mesenchymal GPBP could induce peripheral insulin resistance and drive glucose towards tumor metabolism." (PMID 29541394, 2018). "Additionally, hormonal elements (Osteoc, TESTO, FSH, and insulin), tumor-related proteins (CEA and PSA), and nutrition markers (FERR) might take part in the systematic low-grade inflammation recruiting the leukocytes to EPS." (PMID 28831136, 2017). "Furthermore, the promotion of tumor cell growth upon insulin exposure may differ by breast cancer subtype; we know from in vitro studies that mitogenic potential of insulins depends on the type of breast cancer cell line." (PMID 28076434, 2017). "Therefore, it is difficult to isolate the tumor suppressive impact of these agents attributable to direct effects on metabolic signals in cells versus indirect effects on systemic factors such as reductions in circulating insulin." (PMID 28959684, 2017). "Additionally, from the tumor-associated factors analyzed (VEGF, RANK-L, TNF-alpha and HIF-1alpha) that could be putatively associated to the impaired glucose/insulin metabolism, only VEGF was found overtly elevated in BCa patients compared to controls." (PMID 29113405, 2017). "Furthermore, immunohistochemical analysis of ERK1/2 suggests that activation of insulin signaling may accelerate tumor progression in the hyperglycemic state." (PMID 28903776, 2017).
tumor (continued). "Such host factors include systemic metabolic regulators including insulin, insulin-like growth factor 1, adipokines, inflammation-related molecules, and steroid hormones, as well as the cellular and structural components of the tumor microenvironment, particularly adipose tissue." (PMID 28959684, 2017). "The most frequently proposed hypotheses are the indirect effects of reducing levels of insulin and even insulin-like growth factor 1 (IGF-1), which is closely related to insulin signaling and exerts direct effects on the activation of cellular pathways of tumor cells." (PMID 28409158, 2017). "Likewise, there is also data supporting the contention that the tumor could influence whole body glucose/insulin metabolism through the secretion of certain factors." (PMID 29113405, 2017). "Therefore, the reduction in plasma IGF1 and insulin by MR suggest that the reduced levels in the insulin/IGF1 axis may inhibit tumor development in this xenograft model." (PMID 27255182, 2016). "However, increasing evidence indicates that previous treatment could influence the dependency of the tumor cells on the insulin/IGF system and/or downstream signaling pathways." (PMID 27129151, 2016). "This reduction in the tumor growth by 2-DG could be, in part, due to reduced insulin levels leading to attenuation of the insulin/IGF-1/PI3K/Akt/HIF-1α signaling pathway thereby possibly modulating the various cell cycle regulatory proteins (cyclin D, A, E) involved in the proliferation." (PMID 26135741, 2015). "Its indirect effects are likely to be due to inhibition of hepatic gluconeogenesis, resulting in an improvement in insulin sensitivity and a reduction of blood glucose and circulating insulin levels, which may lead to decreased growth factor-stimulated tumor growth 7,8." (PMID 25417601, 2015). "Moreover, exercise may have a potential beneficial effect on tumor outcome by reducing insulin resistance and insulin/insulin-like growth factor-1 (IGF-1) secretion." (PMID 26458923, 2015). "These recently described roles include GLUT4 trafficking in response to insulin signaling in adipocytes, neuronal growth and neuromuscular synapse formation, cellular invasion of bacteria pathogens and toxins, tumor invasion and cell migration, and cellular autophagy." (PMID 26046524, 2015). "The observed effect of metformin in decreasing tumor development may be due at least in part to its metabolic effects correcting lipid abnormalities, reducing accumulation of adipose tissues and keeping low circulating insulin levels." (PMID 24858012, 2014). "Thus, in early stage HNSCC insulin inhibition through CHO restriction may be beneficial against tumor glycolysis and progression." (PMID 25364576, 2014). "Therefore the overall impact of 2.17-mAlb on tumor growth was determined not only by the direct effects of LepR antagonist on tumor cells and/or other cells supporting tumor growth, but also by other systemic factors such as insulin metabolism that are regulated by leptin." (PMID 24587106, 2014). "First higher insulin levels may contribute to increased tumor growth." (PMID 23837500, 2013). "Thus, persistent diet-induced acidosis favorable for maintaining chronically high levels of cortisol could be supportive of insulin sensitized tumor development." (PMID 22853725, 2012). "However, it is notable that part of the therapeutic benefit of metformin in previous tumor studies may relate to effects on circulating insulin and insulin-like growth factor levels, as well as energy stress." (PMID 22363765, 2012). "Interestingly, administration of insulin was able to reduce the weight loss similar to the ketogenic MCT diet, but at the expense of a 50% increase in tumor size, which could be counteracted by addition of β-hydroxybutyrate in the drinking water." (PMID 22029671, 2011).
tumor (continued). "Moreover, the addition of insulin to hyperglycemic-grown tumour cells further increased proliferation, as well as cell migration, by modifying the expression of molecules involved in cell cycle regulation, signal transduction, cell–cell adhesion and cellular locomotion." (PMID 21179032, 2011). "The insulin-lowering effects of metformin may play a major role in its anticancer activity since insulin has mitogenic and prosurvival effects and tumor cells often express high levels of the insulin receptor, indicating a potential sensitivity to the growth promoting effects of the hormone." (PMID 21470407, 2011). "In addition to modulation of insulin sensitivity, these adipokines can directly affect tumor cells." (PMID 21696633, 2011). "However, insulin-sensitizing, anti-inflammatory, anti-angiogenic, anti-proliferative, pro-apoptotic, and antioxidant mechanisms have been mentioned as possible explanations for the anti-tumor effect of adiponectin." (PMID 21450081, 2011). "The inability of large tumor suppressor proteins, all of which are intracellular, to cross the plasma membrane precludes the therapeutic administration of recombinant tumor suppressors in a manner analogous to administration of extracellular biological therapeutics (e.g., insulin or G-CSF)." (PMID 14966535, 2004). "In the tumours, we found that GLP-1R was localized in the cell membrane and insulin in the cytoplasm, as in the pancreatic β-cells, with clusters of GLP-1R-containing cells." (PMID 41488993, 2026). "Moreover, TORC1 activity cannot be fully restored by hyperactivation of upstream Insulin/PI3K signaling or inhibition of AMP-activated kinase (AMPK) in ACC-deficient tumor cells, but supplementation with ectopic oleic acid can partially increase TORC1 activity and tumor progression." (PMID 41963309, 2026). "Metabolic parameters, plasma biomarkers (including leptin, insulin, IGF-1, adiponectin, and estrone), mammary gland histology, tumor incidence, and gene expression profiles were longitudinally evaluated." (PMID 40806434, 2025). "In hormone-sensitive tissues, leptin interacts with insulin and IGF-1 signalling, forming an endocrine-oncogenic triad that supports tumour progression." (PMID 41586225, 2025). "Given the low levels of insulin, IGF‐I, and C‐peptide, combined with a positive glucagon stimulation test, the possibility of an IGF‐II–secreting tumour was considered." (PMID 40697895, 2025). "Inflammatory cytokines and tumor-derived mediators released into the bloodstream interact with PBMCs, triggering intracellular signaling pathways that upregulate CK19, NANOG, and INS genes." (PMID 40699634, 2025). "Its proposed mechanisms include enhanced insulin sensitivity, reduced circulating insulin and IGF-1 levels, and activation of the AMPK–mTOR signaling pathway, collectively suppressing oncogenic signaling and tumor proliferation." (PMID 41300987, 2025). "Significant reductions in fasting glucose, insulin, and IGF-1 were observed, alongside evidence of immune activation, including increased CD8+T cells and interferon-γ–related tumor signatures." (PMID 41278264, 2025). "The Western diet, characterized by high intakes of red meat, processed foods, and refined sugars, exacerbates insulin and IGF-1 signaling, promoting tumor growth and progression." (PMID 40428567, 2025). "Insulin and IGF‐1 also enhance angiogenesis via VEGF signaling, facilitating tumor vascularization and dissemination." (PMID 40195579, 2025). "FMD is intended to reduce glucose, insulin, and IGF-1 (which can promote tumour growth) levels but induce ketosis and fasting-like metabolic effects." (PMID 41335382, 2025).